IL1B (interleukin 1 beta)
Diseases named in the same sentence as IL1B in open-access papers (continued):
Sharing a sentence is not in itself a finding about the gene and the disease.
inflammation (continued). "Thus, our studies suggest that the ‘5-/12-LOX-BLT1/2-NLRP3-IL-1β’ signaling cascade potentially contributes to NLRP3 inflammasome stimulation and IL-1β synthesis in HDM/LPS-driven neutrophilic airway inflammation." (PMID 34064821, 2021). "SIRS may lead to an acute lung inflammation known as post-perfusion lung syndrome, in which TNF-α, IL-6, IL-8, and IL-1β have a pivotal role." (PMID 33505996, 2020). "Accordingly, Exo-d-MAPPS significantly improved respiratory function, downregulated serum levels of inflammatory cytokines (TNF-α, IL-1β, IL-12, and IFN-γ), increased serum concentration of immunosuppressive IL-10, and attenuated chronic airway inflammation in CS-exposed mice." (PMID 32257769, 2020). "Accumulating evidence has uncovered that CD4+ T cells are critical for the development and progression of chronic intestinal inflammation, and CD4+ T cell-related cytokines (such as TNF-α, IFN-γ, IL-1β, and IL-17) are upregulated in the inflamed mucosa of patients with IBD." (PMID 32547537, 2020). "Therefore, to further evaluate the effects of the EAFPg on lung inflammation, we measured the inflammatory markers TNF-α, IL1-β, and IL-6." (PMID 29675437, 2018). "Activation of PPARγ can decrease endotoxemic-induced, lipopolysaccharide-induced, and hemorrhage-induced acute pulmonary inflammation and injury through inhibition of neutrophil accumulation, ICAM-1 expression, and proinflammatory cytokine (IL-6, IL-1β) production." (PMID 27556035, 2016). "The rats with SP presented with a shorter refractoriness, a higher incidence and duration of AF, an enhanced susceptibility to developing AF, increased mRNA levels of AF-related pro-inflammatory cytokines (IL-6, IL-1β and TGF-β1), as well as marked atrial inflammation and fibrosis." (PMID 25955429, 2015). "SIRS was assessed by serum proinflammatory cytokines (TNF-α, IL-1β, CXCL1, IL-6), ALI was assessed by lung inflammation (lung myeloperoxidase [MPO] activity), and AKI was assessed by serum creatinine, BUN, and glomerular filtration rate (GFR) (by FITC-labeled inulin clearance) at 4 hours." (PMID 24265742, 2013). "Data obtained indicate that finasteride withdrawal induces gut inflammation in adult male rats and that ALLO treatment is able to counteract some of these alterations, such as the increase in the levels of pro-inflammatory cytokines (i.e., IL-1β and TNF-α) and serotonin." (PMID 36358917, 2022). "The reduced bacterial burden observed in mice treated with LPS was associated to a reduced pulmonary inflammation as shown by a lower neutrophil number in BALF and lungs and a decreased mRNA expression of the pro-inflammatory genes Tnfα and Il-6, but not Il-1β and Cxcl1, in lungs." (PMID 35493510, 2022). "In addition, recent evidence indicated that IL-1β and IL-18 act in synergy with IL-23 to promote the differentiation of Th17 cells and IL-17A production that contributes to AHR and neutrophilic airway inflammation." (PMID 35664352, 2022). "Using immunohistochemistry to detect the expression levels of IL-18 and IL-1β in tissues, it was demonstrated that ISO induced an inflammatory response and released inflammatory factors, while Gyp I intervention improved myocardial inflammation in mice with MF." (PMID 36014544, 2022). "In a model of hypercholesterinemia, lack of IL-1α and IL-1β was able to prevent liver inflammation." (PMID 33202693, 2020). "Intestinal levels of IL-1β correlate well with severity of intestinal inflammation and NLRC4 inflammasome deficiency still results in IL-1β production, suggesting other signaling rather than NLRC4 inflammasome plays dominant role in IL-1β production." (PMID 29456533, 2018). "Furthermore, they suppress NLPR3 inflammasome activation to reduce IL-1β and TGF-β/Smads signaling via CD36-mediated TLR4/6-IRAK4/1 signaling in animal and cell models, exhibiting the alleviation of fructose-induced cardiac inflammation and fibrosis." (PMID 27270216, 2016).
inflammation (continued). "For example, pro‐inflammatory mediators including IL‐1β, IL‐6, and TNF‐α promote a reduction in the NAD+/NADH ratio, leading to an impairment in mitochondrial biogenesis, while mitochondrial dysfunction may induce cardiac inflammation via the release of mitochondrial DNA or formation of ROS." (PMID 37365150, 2023). "In contrast, Ly6C‐ cDCs exert minimal effects on both T cell differentiation and ALI development due to their low intrinsic expression of Il‐6 and Il‐1β, although the MEK/ERK/NF‐κB signaling is not inactivated during pulmonary inflammation." (PMID 40789072, 2025). "Indeed, a recent study showed the non-involvement of IL-1β in synovial inflammation and cartilage destruction during collagenase-induced OA and it was suggested that other inflammatory mediators (possibly the alarmins, IL-6 and IL-17) could be responsible for the joint damage." (PMID 33193305, 2020). "While we have not analyzed the molecular mechanism leading to heart inflammation during MS, experimental data has shown that Toll-like receptor 4 (TLR4) stimulation by fatty acids promotes TNF-α, IL-6, and IL-1β gene expression." (PMID 29201273, 2017). "Similarly, MAPK inhibitors SP600125 and SB203580, but not PD98059, significantly reduced TNF-α and IL-1β in BALF of UCP2-Ad + LPS mice compared to UCP2-NC + LPS mice, demonstrating that enhanced UCP2 expression increased LPS-induced lung inflammation via the JNK and p38 MAPK pathways." (PMID 27057102, 2016).
bacterial infection (408 papers, 2005 to 2026). "After obtaining nearly all of the results, we found that the variable “any bacterial infection” was statistically associated with IL-1β (p-value < 0.05), IL-6 (p-value < 0.05), IL-8 (p-value < 0.05), IL-10 (p-value < 0.05), and TNF-a (p-value < 0.05)." (PMID 40732663, 2025). "We found that the expression levels and secretion levels of IL-6, TNF-α and IL-1β were greater in Gpnmb-deficient THP-1 cells than in sgCtrl THP-1 cells upon bacterial infection." (PMID 40038549, 2025). "Elevated IL-1β levels have been reported in numerous models of bacterial infection, including S. aureus, and are strongly linked to systemic inflammation and tissue damage." (PMID 41487507, 2025). "In bacterial infections, proteases from GAS and Pseudomonas aeruginosa can directly cleave Pro-IL-1β, providing new insights into how bacterial infections cause the host high inflammation and pus formation." (PMID 39038050, 2024). "ATG16L1-deficiency induces enhanced IL-1β secretion in dendritic cells in response to bacterial infection." (PMID 39464882, 2024). "As for NLRP-3 inflammasome, research has confirmed that NLRP-3 can be activated in the case of bacterial infection, promoting the synthesis and secretion of downstream IL-1β, IL-18, and other proinflammatory mediators, and then causing extensive tissue damage." (PMID 36157218, 2022). "Cytokines associated with bacterial infections were downregulated (i.e., IL1β, IL6, IL8, TNFα), whereas the anti-inflammatory cytokine IL10 was upregulated." (PMID 36671404, 2022). "Elevated levels of circulating IL-1β have been reported to cause acute inflammatory response in bacterial infection." (PMID 33665221, 2021). "Inhibition of IL-1β production enhances the susceptibility of the host to bacterial infection, a mechanism utilized by some bacteria to overcome the host’s immune response." (PMID 33488991, 2021). "The inflammatory factors TNF-α, IL-6, and IL-1β, are closely associated with the response to bacterial infection." (PMID 34858427, 2021). "The ageing brain seems to be particularly sensitive to inflammation: indeed, a severe bacterial infection, which causes an increase in hippocampal IL-1β, compromises the cognitive status of aged rats more than in younger adult rats." (PMID 32676979, 2021). "Considering that macrophages are exposed to Stx2 as well as other pathogenic factors during bacterial infection, IL-1β was also tested in supernatants from macrophages infected with C600 or 125/99ΔStx2 strains." (PMID 31947665, 2020). "Our findings illustrate that R. australis exploits Atg5-mediated mechanisms to support bacterial infection in association with dampening of the IL-1β-mediated antirickettsial effect in macrophages." (PMID 30297526, 2019). "In contrast, bacterial infections are commonly associated with an extensive release of IL-1β, thereby stimulating the hepatocytic CRP secretion through the induction of IL-6." (PMID 27977798, 2016). "Accordingly, AQP1 ablation in macrophage is associated with a strong reduction of IL1β release and neutrophilic inflammation as confirmed by our in vivo data showing a major effect during bacterial infection." (PMID 25719758, 2015). "The AA genotype has been associated with higher gastric mucosal levels of IL-1β in bacterial infections, while mononuclear cells from subjects with the GG genotype showed an increased release of IL-1β after stimulation with lipopolysaccharide." (PMID 22132000, 2012). "Proinflammatory cytokines such as IL-1β and IL-6 are integral to acute-phase inflammation that is linked to both systemic and metabolic alterations, while also modulating the immune response during bacterial infections." (PMID 41383965, 2025). "This phenomenon is probably because, usually, the level of procalcitonin increases in the presence of cytokines, caused by a bacterial infection (IL-1b, TNF-a, and IL-6), and its production is regulated by the signal transducer and activator of transcription 3 (STAT-3)." (PMID 34439009, 2021).
bacterial infection (continued). "However, it is observed that patients who receive NLRP3 or IL-1β inhibitors are disproportionately susceptible to bacterial infections." (PMID 33424869, 2020). "The production of IFNγ, TLR ligands, TNF-α, PGE2, IL-1β, and IL-6 from T cells or bacterial infection may follow the accumulation MDSCs associated with signal transducer and activator of transcription signaling pathways." (PMID 33212789, 2020). "Recent work has implicated neutrophils in IL1B production upon bacterial infection, suggesting that neutrophils could play more central roles in modulating inflammation." (PMID 31242601, 2019). "Remarkably, introducing increasing amounts of active and extracellular NADase (through increasing numbers of Δslo bacteria) into nga(G330D) bacterial infections caused a decrease in IL-1β levels, while cytotoxicity levels were only slightly but not significantly affected." (PMID 28720729, 2017). "To investigate whether the same mechanism underlies the induction of il1b expression by fin fold amputation and bacterial infection, we injected zebrafish with Salmonella typhosa lipopolysaccharide (LPS), a reagent whose injection mimics bacterial infection." (PMID 28229859, 2017). "Importantly, PB1-F2's role in inducing the inflammasome and IL-1β production is relevant to the phenomenon of secondary bacterial infections; the cause of the majority of IAV related mortalities." (PMID 23737748, 2013). "To study the impact of bacterial infection on host immunological responses, we monitored mRNA levels of genes encoding inflammation markers TNFα, IL-1β, IL-22 and IL-10, including pro- and anti-inflammatory cytokines, in axenic and infected zebrafish larvae at 1, 2 and 3 dpi." (PMID 22911651, 2012). "Interestingly, we would like to emphasize that IL-1β is vital for resolving bacterial infection caused by various pathogens." (PMID 22136135, 2011). "In BCO, IL-1β could be acting not only as a proinflammatory influencer, but as a contributor to decreased cartilage stability and maturation, increasing susceptibility to mechanical stress and bacterial infection." (PMID 34831397, 2021). "Low expression of NLRP1 and NLRP12 might be related to a risk of susceptibility for bacterial diseases, via reduced cleavage of pro-IL-1β and pro-IL-18 to produce mature isoforms, and via avoidance of infected macrophage lysis which contributes to pathology in TB." (PMID 31821366, 2019). "As caspase-1 and IL-1β have previously been associated with resistance to bacterial infections and are also linked to macrophage killing of B. anthracis, we hypothesized that the LT-dependent IL-1β response in Nlrp1bS-expressing mice might explain their relative resistance." (PMID 21170303, 2010). "Thus, secretion of biologically active IL-1β protein may be induced when sleep deprived people are infected (i.e. enhanced susceptibility to viral and bacterial infections), a phenomenon which is frequently associated with chronic sleep deprivation." (PMID 19240794, 2009). "On the other hand, NR2C2 is recognized for its proinflammatory effects during bacterial infections as it augments NFkB expression, thereby fostering the production of IL1B and IL6 in macrophages." (PMID 41516283, 2025). "This double-edged sword of neutrophil inflammation highlights how important the efficient and tight regulation of chemoattractants such as IL-8 and IL-1β are in response to bacterial infections, a regulatory mechanism that is lost in the presence of CepEVs." (PMID 41550953, 2025). "It is plausible that neutrophils were the source of IL-1β in this calf, which probably died of a secondary bacterial infection." (PMID 41150385, 2025). "NEDD4L-deficient cells showed increased GSDM activation, IL-1β release and were significantly more susceptible to cell death induced by NLRP3 agonists, cytotoxic agents, and bacterial infection." (PMID 41261204, 2025).
bacterial infection (continued). "Further analysis of pro-inflammatory factors IL-6 and IL-1β in serum showed that the IL-6 levels in the EI group were significantly lower than in the E group at 3 h and 12 h post-bacterial infection." (PMID 40895560, 2025). "Analysis of proinflammatory cytokines and chemokines at different time points showed significant upregulation of Tnf, Mmp14, Il1b, Il1a, Il17ra, Cxcl1, Cxcl2, Ccrl2, Ccl3, Ccl4, and Ccl9 after bacterial infection." (PMID 41117166, 2025). "The upregulation of pro-inflammatory cytokines, including CXCL8, CXCL10, IL-1β, IL-6 and MMP9 was associated with the progression of host bacterial infection." (PMID 40839565, 2025). "One of the first mediators generated in response to bacterial infections is interleukin-1 beta (IL-1β)." (PMID 40310312, 2025). "IL-1β is a proinflammatory cytokine that has an important role in the immune response after the initial host recognizes bacterial infection and enhances phagocyte recruitment and function." (PMID 40431335, 2025). "Among these, IL-1β is a key proinflammatory cytokine that plays a vital role in the immune response to bacterial infections." (PMID 41303313, 2025). "Here, we show that E. faecalis gelatinase proteolytically activates IL-1β, which is abundant in proximity to vegetation biofilms and is likely released by neutrophils undergoing NETosis in response to bacterial infection." (PMID 39974957, 2025). "In bacterial infections, a CARD9 deficiency results in a decrease in inflammatory cytokines (IL-1β, IL-6, and TNF-α) and chemokines (CXCL1, CXCL2, and CXCL5)." (PMID 38473845, 2024). "LncRNA MEG3-4 competes with the proinflammatory cytokine interleukin-1β (IL-1β) mRNA for binding to miR-138, resulting in elevated levels of IL-1β and enhanced inflammatory responses during bacterial infection." (PMID 39334466, 2024). "The destruction of SSMs is a common feature associated with inflammation and viral or bacterial infection, while QS-21 has been verified to activate ASC-NLRP3 inflammasome and subsequent IL-1β/IL-18 release." (PMID 38750307, 2024). "In bacterial infection, inflammatory cytokines (such as tumor necrosis factor-alpha, IL-1β, and IL-6) induce gene expression responsible for PCT production." (PMID 38698211, 2024). "Given the critical role of IL-1β in mediating host resistance to bacterial infection, we subsequently implemented a blockade of the IL-1β produced by the host." (PMID 39353913, 2024). "In general, IL-1β production has been reported to play several roles in various types of cells in response to bacterial infections, inducing other cytokines and stimulating specific types of adaptive immunity such as Th17 production." (PMID 39042701, 2024). "IL1B is a pro-inflammatory cytokine mediating the immune response of fish to viral and bacterial infection." (PMID 39211041, 2024). "Pyroptosis is an inflammatory programmed cell death pathway that responds to intracellular bacterial infections with unique characteristics: cells rupture and release pro-inflammatory cytokines such as IL-1β and IL-18." (PMID 39042701, 2024). "Of note, the levels of these cytokines, such as KC and IL‐1β were significantly low in the bleomycin model compared to LPS or bacterial infection models." (PMID 39455422, 2024). "We found that IL-18 negatively regulated the exacerbation of skin inflammation induced by the bacterial infection, whereas IL-1β was involved in the control of the bacterial burden." (PMID 37910490, 2023). "In contrast to macrophages, there are relatively few reports on the role of neutrophils as a source of IL-1β during bacterial infection." (PMID 37730693, 2023). "When organisms suffer from the stress of environmental factors, IL-1β participates in activating the inflammatory response and resisting bacterial infection." (PMID 37888662, 2023).